KLK9 (kallikrein related peptidase 9)
Synonyms: KLK-L3; KLKL3
Tractability: Antibody: UniProt places it where antibodies can reach, with high confidence; UniProt predicts a signal peptide or a membrane-spanning region; its Gene Ontology location is reachable by antibodies, with medium confidence.
Gene: Protein-coding gene on chromosome 19 (51,002,508 to 51,009,634, reverse strand). Ensembl gene ENSG00000213022.
Subcellular location: Secreted
Gene Ontology:
Molecular function: serine-type endopeptidase activity
Biological process: protein maturation; proteolysis
Cellular component: secretory granule; extracellular region
Genetic constraint (gnomAD): Loss-of-function variants: 27 observed, 24.94 expected, observed/expected ratio (o/e) 1.08, 90% interval 0.8 to 1.49. The upper end of that interval is the gene's LOEUF score, 1.49, which puts it in group 6 of 6, group 1 being the genes least tolerant of losing a copy. Missense variants: 346 observed, 336.21 expected, observed/expected ratio (o/e) 1.03, 90% interval 0.94 to 1.12. Synonymous variants: 122 observed, 129.7 expected, observed/expected ratio (o/e) 0.94, 90% interval 0.81 to 1.09.
Homologues: Orthologues: chimpanzee KLK9 (100% identical), macaque KLK9 (99% identical), dog KLK9 (89% identical), rabbit KLK9 (88% identical), pig KLK9 (88% identical), rat Klk9 (82% identical), guinea pig KLK9 (81% identical), mouse Klk9 (80% identical). Paralogues in human: KLK15 (48% identical), PRSS33 (36% identical), OVCH1 (35% identical), PLG (34% identical), PRSS57 (32% identical), PRSS27 (32% identical), PLAT (31% identical), PRSS48 (30% identical), TMPRSS12 (30% identical), GZMM (28% identical), PRSS50 (28% identical), PRSS37 (27% identical), and 2 more.
Diseases named in the same sentence as KLK9 in open-access papers:
KLK9 is named in the same sentence as 14 diseases in open-access papers, as found by Europe PMC text mining. Sharing a sentence is not in itself a finding about the gene and the disease. The quoted sentences say what the papers report.
ovarian carcinoma (10 papers, 2002 to 2025). A malignant neoplasm originating from the surface ovarian epithelium. "Four KLKs (KLK4–6 and KLK15) are linked to the poor prognosis of ovarian cancer patients, while higher KLK9 and KLK14 levels are associated with a favorable course of the disease." (PMID 25436002, 2015). "Interestingly, also in in silico analysis–using the same Affymetrix-based ovarian cancer data set from The Cancer Genome Atlas (TCGA) as for KLK9, 10, and 11 –high mRNA levels were associated as a trend (p = 0.068) with a longer OS of ovarian cancer patients." (PMID 29095848, 2017). "In previous studies, KLK9 expression in ovarian cancer has been observed to be significantly higher in patients with earlier stages and low-grade tumors, implicating that KLK9 could be associated with subtypes displaying a less aggressive tumor disease." (PMID 29095848, 2017). "In line with this primary P1 specificity, KLK9 was found in complex with α1-antichymotrypsin in ovarian cancer ascites." (PMID 41516101, 2025). "For example, KLK15 expression is an independent marker of prognosis in ovarian cancer, KLK9 has been shown to be a marker for prognosis in breast and ovarian cancer, and increased KLK11 expression in gastric carcinoma is associated with poor prognosis." (PMID 29707153, 2018). "In ovarian cancer, KLK9 expression levels were found to be significantly higher in patients with early disease stage and to display an inverse correlation with CA125 levels." (PMID 29095848, 2017). "Again pointing to potential tumor specific effects of kallikreins, KLK9 was previously found to be expressed at higher levels in low grade breast and ovarian cancers." (PMID 26231762, 2015). "In the case of ovarian cancer, KLK9 expression is a predictor of longer overall survival in patients with lower grade tumors." (PMID 26231762, 2015). "In contrast, KLK8 and KLK9 expression have been reported to be favorable prognosis in ovarian cancer." (PMID 24510347, 2014). "Hormonal regulation of KLKs in ovarian cancer has only been demonstrated in the ovarian cancer cell line, BG-1, where KLK9 was under the regulation of oestrogen and progesterone." (PMID 17242704, 2007). "Also in ovarian cancer, higher KLK9 mRNA levels have been reported to be an independent favorable prognostic marker." (PMID 29095848, 2017). "In ovarian cancer ascites, the major form was KLK9 bound to a1-antichymotrypsin (see also below)." (PMID 28115917, 2017). "KLK9, 10, 11, and 15 may represent potential cancer biomarkers for evaluating ovarian cancer prognosis." (PMID 29095848, 2017). "Specific regulatory patterns of kallikreins across cancers may be related to hormone regulation, as proposed for KLK9 in both breast and ovarian cancer." (PMID 26231762, 2015). "In addition, higher KLK9 expression is a favorable prognostic marker of ovarian cancer." (PMID 33150763, 2020). "Furthermore, KLK8 and KLK9 expression are higher in ovarian cancer of better prognosis." (PMID 11986781, 2002). "In the present study, we therefore analyzed the expression of KLK9, 10, 11, 15 mRNA in a very homogeneous cohort of patients with advanced high-grade serous ovarian cancer FIGO stage III/IV, encompassing the largest subgroup of patients afflicted with ovarian cancer." (PMID 29095848, 2017).
breast carcinoma (5 papers, 2015 to 2020). "In brief, the mRNA level of KLK9 expression has favorable prognostic value in ovarian and breast cancer, while elevated KLK9 expression levels were associated with higher grade gliomas." (PMID 28115917, 2017). "In breast cancer, higher KLK9 expression is associated with smaller tumor mass, increased patient overall survival, and longer disease-free survival." (PMID 29095848, 2017). "Other studies observed elevated KLK9 expression in the early stages of breast cancer compared with advanced stages and in patients with tumor size <2 cm compared with bigger tumors." (PMID 33150763, 2020). "In brief, KLK9 gene expression was found to have favorable prognostic value in ovarian and breast cancer, while elevated KLK9 expression levels were associated with higher grade gliomas." (PMID 28115917, 2017). "In fact, in breast cancer cells, KLK9 and KLK15 have both been observed to be up-regulated by androgens and possibly also estrogens." (PMID 29095848, 2017). "In breast cancer, KLK9 expression was also higher in patients with smaller tumors and was associated with increased patient survival, particularly patients that are estrogen and progesterone receptor negative." (PMID 26231762, 2015).
glioma (4 papers, 2015 to 2019). A benign or malignant brain and spinal cord tumor that arises from glial cells (astrocytes, oligodendrocytes, ependymal cells). "The current studies are among the first to examine KLK9 in malignancy and results of interest since elevations in tumor KLK9 were found to be associated with higher grade gliomas." (PMID 26231762, 2015). "Conversely, KLK9 has been reported to be associated with higher grade gliomas and may be associated with poor prognosis in this tumor entity." (PMID 29095848, 2017). "The current study provides the first evidence that KLK9 protein expression may be associated with poor prognosis in glioma patients." (PMID 26231762, 2015). "The current work therefore points to the need for additional studies to determine the potential pathophysiological roles of KLK7 and KLK9 in glioma malignancy and any parallel involvement of PAR-activation in mediating their effects." (PMID 26231762, 2015). "The kallikreins KLK6, KLK7, and KLK9 have been shown to have higher protein levels in Grade IV glioma compared to Grade III tumours and consequently may have utility as prognostic markers for patient survival." (PMID 32082376, 2019).
prostate carcinoma (4 papers, 2013 to 2020). A carcinoma that arises from epithelial cells of the prostate gland. "Since the free/total PSA ratio in serum of prostate cancer patients is used for diagnostic and prognostic purposes, this could suggest a similar application of KLK9." (PMID 28115917, 2017). "In this study, KLK1, KLK4, KLK9, and KLK14 were strongly decreased in prostate cancer samples compared with controls." (PMID 33150763, 2020). "In conclusion, we propose that KLK1, KLK2, KLK3 KLK4, KLK8, KLK9, and KLK14, which are differentially expressed in prostate cancer, could be used as promising biomarkers of prostate cancer progression." (PMID 33150763, 2020). "Given that KLK9 and KLK15 are weakly expressed in most tissues including the prostate it is not surprising that no copy number association with prostate cancer was found." (PMID 23894413, 2013). "KLK9 in our study was upregulated in recurrent and non-recurrent prostate cancer tissues." (PMID 33150763, 2020). "Our results point to the fact that KLK1, KLK2, and KLK14 (only in recurrent prostate cancer tissues) are underexpressed in prostate cancer tissues, while KLK3, KLK4, KLK8, and KLK9 are overexpressed in both recurrent and non-recurrent tissues." (PMID 33150763, 2020).
asthma (1 paper, 2017). "Recent studies associate KLK9 expression patterns with cardiac hypertrophy and hypertension-induced target organ damage, psoriatic lesions and complications in asthma patients." (PMID 28115917, 2017). "Recent studies associate KLK9 expression patterns with non-malignant diseases, such as cardiac hypertrophy and hypertension-induced target organ damage psoriatic lesions and complications in asthma patients." (PMID 28115917, 2017).
astrocytoma (1 paper, 2015). "Like KLK6, higher levels of KLK1, KLK7, KLK8, KLK9 and KLK10 were all found to be associated with higher astrocytoma grade." (PMID 26231762, 2015). "Expression of KLK1, KLK6, KLK7, KLK8, KLK9 and KLK10 protein was assessed by immunohistochemical analysis of grade III (n = 8) and grade IV (n = 60, n = 55 for KLK1) astrocytoma samples." (PMID 26231762, 2015). "Through a comprehensive parallel analysis of immunoreactivity for six kallikreins in grade III and IV astrocytoma we determined that tumor core staining for KLK7 and KLK9, like KLK6, has significant prognostic value with regard to patient survival." (PMID 26231762, 2015). "In this study we determined KLK1, KLK6, KLK7, KLK8, KLK9 and KLK10 protein expression in two independent tissue microarrays containing 60 grade IV and 8 grade III astrocytoma samples." (PMID 26231762, 2015).
myeloma (1 paper, 2017). "Purified mat-KLK9 was injected into mice for the production of monoclonal antibodies by somatic cell fusion of murine splenocytes with murine myeloma cells." (PMID 28115917, 2017).
serous ovarian cancer (1 paper, 2017). "KLK9, 10, 11, and 15 mRNA levels were determined by qPCR in tumor tissues of a homogenous cohort (n = 139) encompassing only patients with advanced serous ovarian cancer FIGO stage III/IV." (PMID 29095848, 2017). "In contrast to previous studies, we found that mRNA levels of KLK9 are neither associated with OS nor with PFS in advanced high-grade serous ovarian cancer patients." (PMID 29095848, 2017). "In contrast to KLK9 and 10, in the present study, high KLK11 mRNA levels were found to be an independent favorable predictor for both OS and PFS in advanced high-grade serous ovarian cancer." (PMID 29095848, 2017). "In the present study, we selected a homogeneous cohort including 139 patients of advanced high-grade serous ovarian cancer (FIGO stage III/IV) and assessed the mRNA levels of KLK9, 10, 11, and 15 in tumor tissue by quantitative PCR." (PMID 29095848, 2017). "In the present study, we demonstrate that KLK9 and KLK15 both display low mRNA expression levels in most of the advanced high-grade serous ovarian cancer samples." (PMID 29095848, 2017). "In summary, whereas KLK9 and KLK10 mRNA expression does not display any prognostic power in advanced high-grade serous ovarian cancer (FIGO stage III/IV), high KLK15 and, especially, KLK11 mRNA levels are associated with better outcome." (PMID 29095848, 2017).
cancer (5 papers, 2011 to 2020). A tumor composed of atypical neoplastic, often pleomorphic cells that invade other tissues. "The mRNA expression status of the KLK5, KLK6, KLK7, KLK8 and KLK9 has been extensively studied in cancer." (PMID 29229980, 2017). "Among these target genes, KLK9, WNT3A, FGF18, FIBP, SOX12, TGFBI, and NEDD9 have been reported to participate in the development of human cancers." (PMID 33344223, 2020).
tumor (4 papers, 2015 to 2020). "In addition, an increased percent of tumor immunoreactive for KLK6 or KLK9 was associated with decreased survival in grade IV patients." (PMID 26231762, 2015). "Patients with KLK9 % tumor core stained < 4 (n = 29) had median survival of 422 d; patients with KLK9 % tumor core stained = 4 (n = 31) had a median survival of 311 d (HR = 1.70, CI = 0.98–2.95, P = 0.061)." (PMID 26231762, 2015). "Specifically, higher tumor core levels of KLK6, KLK7 and KLK9 were each associated with reduced GBM patient survival." (PMID 26231762, 2015). "Moreover, as the percent of the tumor core stained positive for KLK6 or KLK9 increased, survival decreased (HR = 1.63, CI = 1.06–2.50, P = 0.03 and HR = 2.25, CI = 1.21–4.22, P = 0.01, respectively)." (PMID 26231762, 2015). "The independent prognostic value of KLK9, 10, 11, and 15 for OS and PFS was studied by multivariable Cox hazard regression analysis, including the factors age, ascites fluid volume, and presence of residual tumor mass (base model)." (PMID 29095848, 2017). "The mean percent tumor core stained for KLK1, KLK7, KLK9 or KLK10 across grades III and IV were not significantly different." (PMID 26231762, 2015).
KLK9 also shares sentences with these, for which no sentence is quoted: cardiac hypertrophy (1 paper); glioblastoma (1); Hypertension (1); psoriasis (1).